MIR373 (microRNA 373)
Synonyms: hsa-mir-373; MIRN373; miRNA373; mir-373
Gene: MicroRNA gene on chromosome 19 (53,788,705 to 53,788,773, forward strand). Ensembl gene ENSG00000199143.
Diseases named in the same sentence as MIR373 in open-access papers:
MIR373 is named in the same sentence as 1 disease in open-access papers, as found by Europe PMC text mining. Sharing a sentence is not in itself a finding about the gene and the disease. The quoted sentences say what the papers report.
tumours (1 paper, 2024). "We identified MIR182, MIR183, MIR371, MIR373, MIR512-1, MIR512-2, MIR515-1, and MIR520e exhibiting high expression and MIR216b, MIR887, MIR9-2, and MIR9-3 exhibiting low expression in NANOG H/L tumours." (PMID 38693576, 2024).